C1QTNF9 (C1q and TNF related 9)
Description:
Probable adipokine. Activates AMPK, AKT, and p44/42 MAPK signaling pathways.
Synonyms: C1QTNF9A; MGC48915; CTRP9; AQL1
Tractability: Antibody: UniProt places it where antibodies can reach, with medium confidence; UniProt predicts a signal peptide or a membrane-spanning region; its Gene Ontology location is reachable by antibodies, with medium confidence.
Gene: Protein-coding gene on chromosome 13 (24,307,166 to 24,322,535, forward strand). Ensembl gene ENSG00000240654.
Subcellular location: Secreted
Gene Ontology:
Molecular function: protein binding
Cellular component: extracellular region
Genetic constraint (gnomAD): Loss-of-function variants: 7 observed, 14.41 expected, observed/expected ratio (o/e) 0.49, 90% interval 0.28 to 0.91. The upper end of that interval is the gene's LOEUF score, 0.91, which puts it in group 3 of 6, group 1 being the genes least tolerant of losing a copy. Missense variants: 183 observed, 293.19 expected, observed/expected ratio (o/e) 0.62, 90% interval 0.55 to 0.71. Synonymous variants: 87 observed, 113.15 expected, observed/expected ratio (o/e) 0.77, 90% interval 0.65 to 0.92.
Homologues: Orthologues: chimpanzee C1QTNF9 (99% identical), macaque C1QTNF9 (95% identical), dog ADIF1 (89% identical), guinea pig ADIF1 (87% identical), rabbit ADIF1 (86% identical), mouse C1qtnf9 (84% identical), rat C1qtnf9 (83% identical), zebrafish c1qtnf9 (55% identical), tropical clawed frog c1qtnf9b (35% identical). Paralogues in human: C1QTNF9B (98% identical), COL8A2 (41% identical), COL10A1 (40% identical), COL8A1 (38% identical), OTOL1 (36% identical), C1QTNF7 (35% identical), ADIPOQ (34% identical), C1QTNF2 (34% identical), C1QTNF5 (30% identical), C1QB (28% identical), C1QC (28% identical), C1QL2 (25% identical), and 11 more.
Diseases named in the same sentence as C1QTNF9 in open-access papers:
C1QTNF9 is named in the same sentence as 78 diseases in open-access papers, as found by Europe PMC text mining. Sharing a sentence is not in itself a finding about the gene and the disease. The quoted sentences say what the papers report.
atherosclerosis (23 papers, 2016 to 2025). A disease characterized by the build-up of fatty material and calcium deposition in the arterial wall resulting in partial or complete occlusion of the arterial lumen. "C1q and TNF-related 9 (C1QTNF9) were indicated to attenuate atherosclerosis through the AMPK-NLRP3 inflammasome singling pathway and were frequently reported in the cardiovascular system." (PMID 36319832, 2022).
cancer (3 papers, 2020 to 2025). A tumor composed of atypical neoplastic, often pleomorphic cells that invade other tissues. "Furthermore, overexpression of C1qTNF9 has been proposed to activate aberrant AKT and MAPK signaling pathways in cancer cells." (PMID 33274048, 2020).
tumor (3 papers, 2017 to 2022). "By real-time qPCR, we further examined the expression of selected genes (Pkm, Ppp1r13l, Vamp3, Ctnnb1, Tbc1d4, Ppp1r21, C1qtnf9, Fgf3 and Efemp2) that are known to be involved in the tumor development or potentially relevant for establishment of malignant transformation." (PMID 29073177, 2017). "QRT-PCR showed that the expression of the ACTA2, C1QTNF9, DNAH8, GATM, LBP, and NGF were significantly downregulated in tumor samples." (PMID 36319832, 2022).
C1QTNF9 also shares sentences with these, for which no sentence is quoted: diabetes (22 papers); coronary artery disease (20); myocardial infarction (18); Obesity (18); type 2 diabetes mellitus (13); Insulin resistance (11); cardiovascular diseases (10); metabolic syndrome (10); cardiac hypertrophy (9); endothelial dysfunction (9); myocardial ischemia (7); Hypertension (6); heart failure (5); cardiac diseases (4); Hepatic steatosis (4); ischemia (4); Pulmonary Artery Hypertension (4); atrial fibrillation (3); coronary atherosclerosis (3); Hyperglycemia (3); lipid metabolism disorder (3); Myocardial fibrosis (3); acute myocardial infarction (2); Apnea (2); asthma (2); calcification (2); central nervous system diseases (2); chronic kidney disease (2); diabetic retinopathy (2); Hypercholesterolemia (2).
A further 45 diseases each share a sentence with C1QTNF9 in 2 papers or fewer.